KRAS (KRas proto-oncogene, GTPase)
Diseases named in the same sentence as KRAS in open-access papers (continued):
Sharing a sentence is not in itself a finding about the gene and the disease.
pancreatic cancer (continued). "Moreover, ferroptosis exacerbates tumor progression in a KRAS-driven pancreatic cancer mouse model via the recruitment and activation of macrophages through a TMEM173/Stimulator of IFN response CGAMP interactor 1-dependent DNA sensor pathway." (PMID 38908072, 2024). "Additionally, miR-183-5p directly promotes PDCD4, a pro-apoptotic molecule, whereas miR-96 has been shown to act as a tumour suppressor in pancreatic cancer by regulating the oncogene KRAS." (PMID 39685620, 2024). "When it comes to proliferation, KRAS can stimulate cell proliferation in pancreatic cancer." (PMID 38338768, 2024). "Furthermore, it is imperative to draw attention to the emerging theme of KRAS-related pancreatic cancer." (PMID 38706597, 2024). "Specifically delivering antisense oligonucleotides or CRISPR/Cas9 via exosomes to target mutant KRAS in PCCs may also be a novel way to treat pancreatic cancer." (PMID 39054529, 2024). "Furthermore, YAP1 activation is an important mechanism in driving pancreatic tumor growth in KRAS-independent PDAC recurrence." (PMID 38247878, 2024). "In addition, a SOCS7-based biodegrader enabled the degradation of endogenous KRAS oncoprotein in pancreatic cancer cells, ultimately leading to the cells’ proliferation inhibition." (PMID 38746666, 2024). "Glutamine may support the growth of pancreatic cancer through oncogenic KRAS-regulated metabolic pathways." (PMID 39588377, 2024). "Sticking to KRAS-related pancreatic cancer research not only contributes to a deeper understanding of the pathobiology of pancreatic cancer but can also promote the development of treatment strategies, the refinement of individualized therapy, and the advancement of translational medicine." (PMID 38706597, 2024). "Although it has not been tested in pancreatic cancer with KRAS mutation, the nature of its inhibition makes this drug a very promising one." (PMID 38607041, 2024). "In the case of Bxpc3 cells, which do not possess KRAS mutation generally found in pancreatic cancers, LA and αLA induced an intensive effect of cell death via ferroptosis pathway." (PMID 38388563, 2024). "Finally, we verified the broader relevance of the QSP model, the digital twins, and findings on the importance of Tscm enrichment by predicting kinetics for two patients with pancreatic cancer treated with KRAS G12D targeting T cell therapy." (PMID 38278838, 2024). "Here, we investigated whether HIPK2 contributes to oncogenic KRAS-driven tumorigenesis in vivo, in the onset of pancreatic cancer." (PMID 39342278, 2024). "Additionally, decreased expression of miRNA-143 in metastatic pancreatic cancer tissues leads to activation of the KRAS signaling pathway and elevation of E-cadherin levels." (PMID 39200178, 2024). "Indeed, it has been demonstrated that KRAS gene dosage can determine phenotypic characteristics and influence outcome of pancreatic cancer models in vivo." (PMID 38168062, 2024). "Their analysis of tumor tissue from almost 2500 patients with pancreatic cancer revealed that those lacking mutations of the KRAS gene (KRAS WT) frequently harbored mutations of genes associated with various critical cellular functions." (PMID 39410042, 2024). "We are at a breakthrough point in attempts to target KRAS in pancreatic cancer." (PMID 38310130, 2024).
pancreatic cancer (continued). "The results revealed that hTERT-HPNE cells had relatively low FTH1 expression, whereas the FTH1 levels in the KRAS-mutant pancreatic cancer cell lines Mia PaCa-2 and SUIT-2 were approximately 18- and 13-fold higher, respectively, than those in hTERT-HPNE cells." (PMID 39294443, 2024). "Furthermore, the potential of engineered exosomes loaded with siRNA targeting KRAS in reducing tumor growth in pancreatic cancer models." (PMID 39200273, 2024). "This hypothesis is supported by data generated from the combination of the KRAS-G12C inhibitor sotorasib with MTX-531 in mice bearing KRASG12C-mutant CRC or pancreatic tumors." (PMID 38992135, 2024). "KRAS activation is an early event in the pathogenesis of pancreatic cancer." (PMID 38962271, 2024). "FGFR3 and ARID1A mutations may represent actionable targets in TACSTD2-high urothelial cancer, while KRAS mutations may be an attractive target for TACSTD2-high CRC and pancreatic cancer." (PMID 38986529, 2024). "Protein–protein interaction disruptor molecules that displace PDE6d from KRAS by binding to the prenyl‐binding pocket of the PDE proved to be effective in inhibiting oncogenic KRAS signaling and showed some efficacy in models of pancreatic cancer at micromolar concentrations." (PMID 39673076, 2024). "Optimisation of ADT-007 led to improved pharmacokinetic properties, generating pro-drug ADT-1004, of inhibiting both MAPK and AKT pathway activation in KRAS G12C, G12D, G12V, and G13Q, and reducing tumour volume in patient or cell line derived xenograft KRas-mutant pancreatic cancer mouse models." (PMID 39372214, 2024). "While there was a clinical trial for sotorasib in KRAS G12C mutated pancreatic cancer, NCT05251038, there are no published results as the trial was withdrawn, and no further information is available." (PMID 38607041, 2024). "Furthermore, we validated that inhibiting the lysosomal calcium channel TRPML1 effectively induced cell death in KRAS-mutant pancreatic cancer cells." (PMID 38672219, 2024). "In pancreatic cancers, KRAS alterations in the Ras/Raf/MEK/ERK pathway were mainly observed." (PMID 38672586, 2024). "From the dose–response results, we selected two of the most efficient PPRHs for each gene, G4-C and I1-T for MYC-targeting PPRHs and PR-C and PPRH 2 for KRAS-targeting PPRHs; these PPRHs were also the most effective against the pancreatic cancer cell line, AsPc-1." (PMID 39457457, 2024). "KRAS displayed two hotspots in pancreatic cancer, including the well-known KRAS-12 and KRAS-61." (PMID 38473427, 2024). "To further confirm the role of FTH1 in KRAS-mutant-mediated pancreatic cancer cell growth, we assessed whether FTH1 overexpression can restore the effect of FTH1 knockdown on cell viability." (PMID 39294443, 2024). "Occasional instances of RET rearrangements have been described in breast carcinomas, KRAS mutation-negative pancreatic cancers, and some other tumor types." (PMID 38612902, 2024). "Moreover, using an animal model we show that a one-time pancreatic infection with CVB3 in control mice is transient, but in the presence of oncogenic KRas drives chronic inflammation and rapid development of pancreatic cancer." (PMID 39627248, 2024). "Furthermore, we explored the impact of TRPML1 inhibition on the metabolomic profile of KRAS-mutant pancreatic cancer cells." (PMID 38672219, 2024). "In pancreatic cancer, the dosage of mutant KRAS underpins particularly aggressive phenotypes." (PMID 38576709, 2024).
pancreatic cancer (continued). "Such enhanced uptake of exosomes might be mediated by oncogenic KRAS, which promoted macropinocytosis in pancreatic cancer." (PMID 39054529, 2024). "This association held true, even in the subgroup that received chemotherapy, highlighting the independent negative prognostic impact of the G12D KRAS mutation in unresectable pancreatic cancer." (PMID 38666907, 2024). "While SMAD4 loss is not an initiator of pancreatic cancer, it can promote tumor progression usually initiated by KRAS activation." (PMID 38607041, 2024). "To investigate the contribution of HIPK2 to oncogenic KRAS-driven tumorigenesis in the onset of pancreatic cancer, we first assessed the expression of HIPK2 in human PDACs by WB, employing highly specific anti-HIPK2 Ab previously validated on human HIPK2-null cells and tissue microarrays." (PMID 39342278, 2024). "Kirsten rat sarcoma viral oncogene homolog (KRAS) may influence pancreatic cancer development through various metabolic alterations." (PMID 39640479, 2024). "However, most of the KRAS-mutant pancreatic cancer cell lines demonstrated lower FTL levels than did hTERT-HPNE cells." (PMID 39294443, 2024). "These gain-of-function mutations have been identified primarily in IPMN (approximately 65%), subsequently in adenocarcinoma derived from IPMN, and have been reported to not be mutually exclusive with KRAS mutations in pancreatic cancer." (PMID 39126005, 2024). "For example, KRAS mutation testing was not routinely performed in one case diagnosed in 2009, which was early in the era of mutation testing for pancreatic cancer, and not all patients were tested using the DNA- and/or RNA-based gene fusion panels." (PMID 39410042, 2024). "Interestingly, it appears that PDE4D regulates mTORC1 activity, cell size, and cell proliferation in KRAS-mutant (AsPC-1) compared with non–KRAS-mutant (BxPC-3) pancreatic cancer cells." (PMID 37427586, 2023). "Indeed, therapeutic concepts have been proposed, for example, for KRAS mutant pancreatic cancer, in which the combined inhibition of mTORC1/2 and MEK precludes adaptive resistance." (PMID 37946160, 2023). "In pancreatic cancer cells, VMP1 expression is induced by mutated KRAS." (PMID 37629161, 2023). "Some authors consider the determination of KRAS status important, as patients with wild-type KRAS pancreatic tumors represent a distinct subgroup that may benefit from further molecular profiling with a higher probability of discovering targetable mutations." (PMID 37999114, 2023). "Importantly, we demonstrated the suppression of a pancreatic cancer tumor that is very resistant to existing treatments through directly inducing KRAS protein degradation with a CANDDY molecule, TUS-007." (PMID 37513471, 2023). "Notably, a different approach, based on a first-in-class KRAS p.G12D selective degrader (ASP3082) is currently being evaluated in pancreatic cancer patients." (PMID 37835519, 2023). "Another study confirmed that the use of an NRF2 activator together with a glutaminase inhibitor could offer a novel therapy for the treatment of KRAS-dependent pancreatic cancer." (PMID 36975494, 2023). "Additionally, only 1 of the established mutant KRAS-reactive TCR sequences was obtained from a patient with pancreatic cancer, while we report 38 candidates from two patients with pancreatic cancer." (PMID 37776855, 2023). "The ubiquitination-associated Ras signaling pathway, especially KRAS mutation, strongly might participate in the regulation of FTI-277-targeted therapy for pancreatic cancer." (PMID 37540295, 2023). "Importantly, KRB-456 is effective at thwarting the in vivo growth of subcutaneous and orthotopic tumors from pancreatic cancer patients with mt KRAS G12D and G12V who have relapsed after chemotherapy and radiotherapy." (PMID 38051103, 2023).
pancreatic cancer (continued). "In addition, FAM83H expression was transcriptionally controlled by MYC in liver cancer cells, and FAM83H overexpression was significantly associated with KRAS mutation and EMT gene signature in pancreatic cancer." (PMID 37761326, 2023). "Additionally, our differentially expressed genes are enriched for expected gene sets such as pancreatic cancer, epithelial mesenchymal transition, and KRAS signaling." (PMID 37034706, 2023). "Indeed, inhibition of IGF1/AKT signalling alongside c-MYC or KRAS inhibition increased pancreatic cancer cell clearance and delayed tumour recurrence in these mice." (PMID 37608096, 2023). "Following these results the authors validated their finding through mining CRISPR–cas9 dependency data, drug screens and western blot endpoints showed that targeting CDK hyperactivation may be an effective way of treating KRAS mutant pancreatic cancer." (PMID 36961757, 2023). "Pancreatic cancer cells with mutant KRAS require strong basal autophagy for viability and growth." (PMID 37996408, 2023). "Taken together, we demonstrated that endogenous KRAS mutations could be corrected by the universal pegRNA in HEK293T/17 cells, pancreatic cancer cell lines, and colon cancer cell lines." (PMID 37391511, 2023). "In addition, mutant KRAS G12V-specific TCR transduced T cells were developed for pancreatic cancer treatment (NCT04146298, Phase I/II)." (PMID 37376135, 2023). "Yet, targeting KRAS farnesylation to globally modulate KRAS activity could also be a therapeutic option for pancreatic cancer." (PMID 37958351, 2023). "Previous studies have targeted KRAS and other genes in pancreatic cancer." (PMID 37794108, 2023). "Although KRAS mutations occur early in the development of pancreatic cancer, they are not necessarily involved in disease progression." (PMID 36262061, 2023). "The anti‐tumor activity of KR12 was also confirmed for KRAS‐driven pancreatic tumors in PKF mice, with no observable loss in body weight." (PMID 36262061, 2023). "Therefore, the KRAS signaling pathway is considered one of the most important targets to develop novel agents to treat pancreatic cancer." (PMID 37174108, 2023). "In keeping with this observation KRAS mutations have been found by several studies to be associated with increased VTE risk across a spectrum of human malignancies, namely in colorectal, lung, and pancreatic cancers." (PMID 38188342, 2023). "Additionally, the oncogenic KRAS mutation-suppressed pancreatic tumor suppressor F-box and WD repeat domain-containing 7 (FBW7) suppressed glycolysis in pancreatic cancer cells and improved the effectiveness of gemcitabine in xenograft models." (PMID 36831413, 2023). "However, exosomes, which are small extracellular vesicles (40–150 nm) released during the fusion of multivesicular bodies with the plasma membrane, have therapeutic potential to control KRAS-dependent pancreatic cancer." (PMID 36975494, 2023). "Other approaches to achieve extrahepatic delivery include direct local instillation, e.g., surgical implantation of depot delivery systems such as anti-KRAS siRNA in the “LODER “device for pancreatic cancer or intrathecal injection of mRNA splice modifying ASOs for spinal muscular atrophy." (PMID 37298407, 2023). "In addition, P8 decreased ERK activation by 50–80% in MGKRAS003, MGKRAS004, and MGKRAS005, indicating that C14 and P8 significantly inhibit KRas-dependent signaling pathways in primary pancreatic cancer cell cultures." (PMID 37813486, 2023). "KRAS is the most frequent genetic alteration in pancreatic cancer (>90%)." (PMID 37174108, 2023). "Similarly, our group found that autophagy is crucial for the turnover of lipids from intracellular lipid stores (i.e., lipid droplets) in KRAS mutant pancreatic cancer." (PMID 36675307, 2023).
pancreatic cancer (continued). "In addition, recent data have shown that restoration of WT KRAS in pancreatic cancer cells induces inhibition of nuclear translocation of YAP1, which is associated with poor prognosis in PDAC patients." (PMID 37298264, 2023). "However, in pancreatic cancer, oncogenic KRAS activates the ERK pathway, which, in turn, phosphorylates KLF11, and abrogates KLF11/SIN3a interaction, leading to transcriptional activation of SMAD7 and tumor progression." (PMID 37239940, 2023). "They found that pancreatic cancer cells could release exosomes containing the KRAS G12D protein, which were taken up by macrophages through an AGER-dependent mechanism." (PMID 37670322, 2023). "Additionally, it is the most effective small molecule inhibitor of KRAS-PDEδ reported to date, suggesting its potential as a therapeutic agent for the treatment of pancreatic cancer." (PMID 37669923, 2023). "We observed that NT5E expression was associated with several gene sets linked to amoeboid migration and pancreatic cancer progression, such as transforming growth factor–β (TGF-β), KRAS, WNT, nuclear factor κB (NF-κB) and IL-6/JAK/STAT3 signaling, hypoxia, or EMT." (PMID 37851808, 2023). "Firstly, we used three KRAS mutant pancreatic cancer cell lines (Patu-8988T, MiaPaca2 and T3M4) and one normal human epithelial pancreatic cell line (HPNE), and compared basal gemcitabine sensitivity using IC50 analysis, assessing cell proliferation after a 72 h treatment." (PMID 37408249, 2023). "In addition, our research team identified several unique compounds with potent anticancer activities against colon cancer cells and pancreatic cancer cells, disrupting the KRas signaling pathway and producing specific cell death via apoptosis." (PMID 37813486, 2023). "KRAS plays a vital role in the development of pancreatic cancer of the PDAC subtype." (PMID 36975494, 2023). "In mouse models, KRB-456 inhibits P-MEK, P-AKT, and P-S6 levels in vivo and inhibits the growth of subcutaneous and orthotopic xenografts derived from patients with pancreatic cancer whose tumors harbor KRAS G12D and KRAS G12V and who relapsed after chemotherapy and radiotherapy." (PMID 38051103, 2023). "Evaluating the K20 model across lung, colorectal and pancreatic cancers within the TCGA datasets revealed several specific molecular subsets that have increased KRAS dependency, such as the progenitor and squamous clusters, as well as copy number-high pancreatic cancers." (PMID 37141389, 2023). "Efforts at targeting KRAS in pancreatic cancer have been unsuccessful so far." (PMID 37404765, 2023). "This oncogene-mediated EV uptake could be a therapeutic target of a drug delivery system for siRNA delivery in KRAS mutant pancreatic cancer." (PMID 37823055, 2023). "Pancreatic cancer patients with non-aneuploid copy number were predicted to be less sensitive to KRAS loss than patients with copy number aberration." (PMID 37141389, 2023). "Therefore, KRAS protein trafficking is successfully inhibited by statin treatment in pancreatic cancer." (PMID 36975494, 2023). "Additionally, the KRAS oncogene plays a critical role in the initiation and maintenance of pancreatic tumors and its signaling network represents a major target for therapeutic intervention." (PMID 37927794, 2023).